C3 (complement C3)
Diseases named in the same sentence as C3 in open-access papers (continued):
Sharing a sentence is not in itself a finding about the gene and the disease.
periodontitis (31 papers, 2008 to 2025). An acute or chronic inflammatory process that affects the tissues that surround and support the teeth. "In humans, it was reported the presence of complement metabolites in the GCF during periodontal tissues inflammation, whereas periodontitis treatment was associated with reduced complement C3 activation." (PMID 39620241, 2025). "The observed associations of C3 and C3c with periodontitis suggest that inhibition of these proteins can improve the treatment of the disease." (PMID 32681659, 2021). "The aim of this study was, first, to determine the value of salivary C3 and C3c as diagnostic biomarkers for periodontitis and, secondly, to determine if C3 and C3c levels had biomarker potential in monitoring periodontal treatment." (PMID 32681659, 2021). "Constitutive complement activation is strongly associated with periodontitis because C3-deficient mice as well as C5aR1 antagonist treated mice are protected against periodontitis." (PMID 31749804, 2019). "Studies of salivary levels of the complement components C3 and C4 have revealed an association of periodontitis with lower levels of C3 found in saliva as compared to healthy controls." (PMID 24944840, 2014). "Animal studies have shown that periodontitis is associated with local microbiologically induced complement activation, and therapeutic inhibition of C3 has been suggested as promising therapeutic options for periodontitis which has already entered clinical trials." (PMID 36960056, 2023). "Previously, salivary levels of total C3 and C4 have been associated with periodontitis." (PMID 32681659, 2021). "Interestingly, C3-deficient mice also exhibited reduced periodontal bacterial load in P. gingivalis-induced periodontitis as compared to wild-type littermate controls." (PMID 30915073, 2019). "Consistent with the importance of complement involvement in periodontal disease pathogenesis, C3-deficient mice were protected against periodontitis in three distinct models, ligature-induced periodontitis, P. gingivalis-induced periodontitis, and aging-associated periodontitis." (PMID 30915073, 2019). "In the periodontal microenvironment of periodontitis mice, the expression levels of C3 in fibroblasts were significantly elevated compared to healthy mice." (PMID 40240339, 2025). "We also detected higher C3 expression in human periodontitis gingiva, indicating its involvement in the disease." (PMID 40801798, 2025). "At the same time, we validated in vivo, using immunofluorescence co-staining, that the fibroblast-derived C3 levels were higher in the periodontitis group compared to the normal group." (PMID 40240339, 2025). "Previous studies have demonstrated the importance of sustained neutrophil infiltration in the progression of periodontitis, with C3 known to recruit neutrophils and contribute to the formation of neutrophil extracellular traps." (PMID 40801798, 2025). "Gene expression analysis of C3 and C3aR revealed that fibroblasts were the primary cell type expressing C3 and macrophages were the primary cell type expressing C3aR in both normal and periodontitis groups." (PMID 40240339, 2025). "Cp40 is able to interrupt the complement cascade by blocking the binding of C3 to its convertase, making this molecule a potential adjunctive treatment option for periodontitis." (PMID 39620241, 2025). "In our study, by analyzing single-cell sequencing data from mouse model of periodontitis, we identified that C3 is primarily derived from periodontal fibroblasts." (PMID 40240339, 2025). "The central component of the complement system, C3, plays a pivotal role in the initial and progression of periodontitis." (PMID 40240339, 2025). "AMY-101 is a promising therapeutic agent for periodontitis due to its targeted modulation of the complement system, specifically through selective C3 inhibition." (PMID 40364839, 2025).
periodontitis (continued). "AMY-101’s selective inhibition of C3 effectively modulates the complement cascade, blocking the production of pro-inflammatory factors like C3a and C3b, which are central to the inflammation and tissue damage seen in periodontitis." (PMID 40364839, 2025). "Understanding the source and mechanism of C3 complement in periodontitis is of great significance for comprehending the pathological development of the disease and can provide a new perspective for designing drug schemes." (PMID 40801798, 2025). "Histological observations indicate that C3-activated complement fragments are abundant in the gingival crevices of periodontitis and positively correlate with inflammatory indices." (PMID 38472293, 2024). "The expression of C3, C3b, and C4b was also discovered to be elevated in the gingival tissue of individuals with periodontitis, and its expression was found to be positively connected with the severity of the condition." (PMID 38218802, 2024). "Their findings indicated elevated salivary levels of total C3 and C3dg complement fragment in patients with either Grade B or Grade C periodontitis compared to the healthy controls." (PMID 37834046, 2023). "Within this context, it is unsurprising that gingival inflammation in patients with periodontitis correlates with elevated complement C3 activity, while successful periodontal treatment results in decreased C3 activation." (PMID 37834046, 2023). "The machine learning algorithms here detected several recognized periodontitis biomarkers or inflammatory factors, including C3, C4A, CRCR4, and CXCL1, confirming the algorithms’ accuracy." (PMID 36457739, 2022). "Salivary levels of another complement factor, C3 and its split factor, C3c, have been compared in saliva of periodontitis patients, before and after periodontal treatment." (PMID 36145415, 2022). "Next, to determine if C3 and C3c levels had biomarker potential in diagnosing and monitoring periodontitis and its treatment." (PMID 32681659, 2021). "The C3-positive cell count was significantly increased in the TR group compared with the control, gingivitis and periodontitis groups (p ≤ 0.05)." (PMID 33803323, 2021). "The inhibition of either C5aR or C3 in murine periodontitis models led to decreased inflammatory levels and tissue destruction." (PMID 33803323, 2021). "In the present study, we showed a significantly increased number of C3-positive cells in the TR group compared to the control, gingivitis and periodontitis groups." (PMID 33803323, 2021). "T2DM‐related upregulation of C3 contributes to the development of periodontitis by promoting macrophages M1 polarization and inhibiting M2 polarization, triggering a pro‐inflammatory effect on periodontal tissues." (PMID 32794619, 2020). "Deletion of C3 has been shown to effectively inhibit the destruction of periodontal tissue and alveolar bone resorption in a periodontitis mouse model." (PMID 32794619, 2020). "In the present study, the levels of C3 in blood and gingival crevicular fluid (GCF) of patients were measured first, and a C3‐knockout diabetic mouse model was established to study the roles of C3 in the progression of T2DM‐related periodontitis." (PMID 32794619, 2020). "Studies demonstrated that C3 activation is a central element in the development of periodontitis in mice." (PMID 31749804, 2019). "Finally, a link has been established between C3 from senescent fibroblasts and neutrophil infiltration in periodontitis." (PMID 40801798, 2025). "Interestingly, compared to the normal group, periodontitis group exhibited significantly increased expression levels of C3 in fibroblasts and C3aR in macrophages within the periodontal tissues." (PMID 40240339, 2025). "Notably, after the onset of periodontitis, the expression of the C3 gene in periodontal fibroblasts and the C3ar1 gene in macrophages both significantly increased." (PMID 40240339, 2025).
periodontitis (continued). "In the present systematic review, complement C3 was constantly over‐expressed in periodontitis patients, supporting the central role of this protein in the alterations of the immune system related to the onset and progression of periodontitis." (PMID 39620241, 2025). "Therefore, our findings clearly demonstrate the destructive role of fibroblast-derived C3 in ligature-induced periodontitis, driven by macrophage M1 polarization and osteoclast differentiation." (PMID 40240339, 2025). "Both studies have agreed on the relevance of C3 inhibition in periodontitis." (PMID 39439802, 2024). "Therefore, C3 is currently identified as one of the 21 most promising candidate genes for periodontitis treatment." (PMID 38472293, 2024). "Previous studies have proposed complement C3 as a potential therapeutic target for periodontitis." (PMID 37834046, 2023). "In contrast, complement C1q, FB, Bb, C3, C3a, C3b, C3c, C3d, C4, C5, C5a, C5b and C9 have all been detected in diseased periodontal tissue and in the gingival crevicular fluid from patients with established periodontitis." (PMID 35572583, 2022). "A study showed that suppressing component 3 (C3) in the complement cascade directly inhibits periodontal inflammation and indirectly counteracts dysbiosis, thus showing promising clinical potential for treating periodontitis." (PMID 36545026, 2022). "Finally, a downregulation of C3 genes has been demonstrated in gingival biopsies from patients recently treated for periodontitis compared with biopsies collected from periodontally healthy controls." (PMID 32681659, 2021). "While measurement of C3 levels in blood is used to screen for specific inflammatory medical diseases such as systemic lupus erythematosus, the inflammatory oral disease periodontitis is diagnosed based on clinical and radiographic recordings." (PMID 32681659, 2021). "C3 concentrations in GCF of diabetic patients may also be a potential indicator of T2DM‐related periodontitis." (PMID 32794619, 2020). "Thereafter, further investigation into whether C3 mediates the development of periodontitis in T2DM patients is necessary." (PMID 32794619, 2020). "A C3‐knockout diabetic mouse model was established, real‐time PCR, Western blotting and histological investigation were performed to evaluate the progress of periodontitis." (PMID 32794619, 2020). "In the present study, we concentrated on whether C3 mediates the development of periodontitis in T2DM." (PMID 32794619, 2020). "This study identified some 20 proteins which were differentially expressed in periodontitis saliva and most, including MMP-8, MMP-9, α2-macroglobulin, and complement C3, have previously been identified as potential biomarkers in conventional analysis of periodontitis saliva." (PMID 24944840, 2014). "As these cytokines were expressed within normal range in periodontitis sites following periodontal therapy, the decreased expression of C3 may further indicate a normal inflammatory status that is reached following periodontal therapy." (PMID 18606014, 2008). "In vitro experiments further confirmed that periodontitis gingival fibroblasts secreted higher levels of C3 protein at 30 ng/ml compared to healthy fibroblasts at about 20 ng/ml, and Pg-LPS stimulation could enhance C3 secretion by gingival fibroblasts from baseline at 10 to about 20 ng/ml." (PMID 40801798, 2025). "Among them, complement C3, profilin‐1, S100A8, and fibrinogen were consistently increased in periodontitis cases." (PMID 39620241, 2025). "Among these, complement C3, profilin‐1, SA100A8, and fibrinogen were consistently reported as increased in periodontitis, while cystatin‐SN and leukocyte elastase inhibitor were more elevated in periodontally healthy controls." (PMID 39620241, 2025).
periodontitis (continued). "Further analysis of the C3 pathway showed that the C3 receptor–ligand pair was active in the communication between CD81+ fibroblasts and neutrophils in both healthy and periodontitis conditions, underscoring its unique role in neutrophil recruitment." (PMID 40801798, 2025). "Studies have demonstrated that the complement system is overactivated during periodontitis and that AMY-101 (C3 inhibitor) targets its complement component (C3) with therapeutic benefit and no adverse toxicity." (PMID 36575471, 2022). "Elevated C3 levels have been identified in oral fluids, such as GCF and saliva of gingivitis and periodontitis patients." (PMID 36145415, 2022). "We propose that this subgroup of fibroblasts can directly promote the progression of periodontitis by secreting SASP-related factors, such as IL-6, and indirectly amplify inflammation by recruiting neutrophils through the complement pathway, specifically C3." (PMID 40801798, 2025). "Furthermore, metformin reversed the elevated expression of C3 and MPO in periodontitis, compared to the periodontitis and ddH2O groups." (PMID 40801798, 2025). "In human periodontitis gingiva, we found that CD81+ fibroblasts might activate neutrophils via the C3/C3aR1 axis to exaggerate inflammation." (PMID 40801798, 2025). "For example, total C3 and C5 have been demonstrated present in gingival biopsies from patients with periodontitis but absent in biopsies from healthy individuals." (PMID 32681659, 2021). "C3 inhibitors were tested in non-human primate models of periodontitis and hemodialysis inflammation, with promising results." (PMID 32635578, 2020). "In Aurer study on different groups including chronic periodontitis patients, healthy group, and patients with tooth loss showed that in addition to TNF-α, salivary levels of other inflammatory factors such as C3, CRP, and α-2M were lower in periodontitis group compared to other groups." (PMID 29238418, 2017). "Local inhibition of C3 reduced experimental periodontitis in non-human primates, and this strategy has been suggested as a treatment in humans." (PMID 27745832, 2016). "Complement C3, keratin (type I and type II), profilin‐1, S100A8, cystatin‐SN, alpha‐2‐macroglobulin, leukocyte elastase inhibitor, and fibrinogen were the proteins consistently over‐expressed or under‐expressed in periodontitis patients in at least three papers." (PMID 39620241, 2025). "Given the absence of available C3 inhibitors in mice, the appropriateness of C3 as a therapeutic target in periodontitis could only be tested in primates." (PMID 30915073, 2019).
type 2 diabetes (31 papers, 2007 to 2024). "Human pancreatic islets highly express C3 and are associated with the donor status of type 2 diabetes." (PMID 35281591, 2022). "For example, elevated serum complement C3 confers risk for coronary heart disease and type 2 diabetes." (PMID 21852021, 2012). "Type 2 diabetes, which is often present in patients with NASH, is also known to be associated with high systemic concentrations of C3." (PMID 25299043, 2014). "Its role in nephropathy is supported by the presence of activated C3 in glomeruli and glomerular capillaries of animal models of type 1 and type 2 diabetes." (PMID 22282163, 2012). "In addition, water T2 is strongly and inversely correlated with complement C3, C4, fibrinogen, and haptoglobin, markers predictive of incident type 2 diabetes." (PMID 30237882, 2018). "Interestingly, some of the down-regulated proteins are known to participate in inflammation (mast cell protease-1, complement C3, T-kininogen 1), adipose tissue metabolism (3-ketoacyl-CoA thiolase B), and oxidative stress (peroxiredoxin-1), or related to steatosis and type 2 diabetes (fetuin-B)." (PMID 31258482, 2019).
dense deposit disease (30 papers, 2010 to 2026). "In contrast, in dense deposit disease, low serum C3 level is typical and commonly associated with the presence of C3NeF." (PMID 22503529, 2012). "The presence of C3NeF can cause excessive C3 consumption, but clinical signs associated with this autoantibody fit in better with Dense Deposit Disease (DDD) and partial lipodystrophy (PLD)." (PMID 22710145, 2012). "Complement factor 3 glomerulopathy (C3G) is caused by dysregulation of the alternative complement pathway (AP), resulting in either dense deposit disease or complement factor 3 (C3) glomerulonephritis." (PMID 38899188, 2024). "It is associated with an abnormal complement activator, the C3 nephritic factor (C3NeF), low C3 levels, and membranoproliferative glomerulonephritis type II (MPGN II)." (PMID 25688346, 2015). "MPGN II which is also called dense deposit disease, is characterized by complement component 3 (C3) containing dense deposits in the glomerular basement membrane that are a result of a dysregulation of the complement alternative pathway." (PMID 23227086, 2012). "As examples, an earlier study on local complement activation in otitis media in children reported an up to 40% level of C3 activation and in dense deposit disease a nearly 100% level of C3 activation in blood plasma could be reached." (PMID 33505390, 2020). "Types I and III MPGN, which exhibit deposits of IgG and C3 on immunofluorescence (IF), are now considered as MPGN caused by IC (IC-MPGN), while type II MPGN, also known as dense deposit disease (DDD), and all the forms with isolated/predominant C3 IF-deposits, are considered as C3G." (PMID 32478016, 2020). "Decreased blood C3 levels have been observed in some less common renal diseases (e.g. atypical hemolytic uremic syndrome, dense deposit diseases, and C3 glomerulonephritis), perhaps due to aberrant complement activation or impaired glomerular filtration barrier and proteinuria." (PMID 30791918, 2019). "Dense deposit disease (DDD) is a rare renal disease related to the dysregulation of the alternative pathway of the complement cascade, caused by several factors including the presence of an autoantibody to C3 nephritic factor, mutations in factor H and autoantibodies to this protein." (PMID 24338037, 2014). "C3G is used as a collective term for dense deposit disease (DDD) and C3 glomerulonephritis (C3GN) and is thought to sometimes occur in postinfectious settings (C3-PIGN)." (PMID 41537099, 2026). "It is distinguished from another C3G, dense deposit disease (DDD), by the location of C3 deposits, which can be subendothelial, intramembranous, or subepithelial, while the deposits are intramembranous with a ribbon-like appearance in DDD." (PMID 34658305, 2021).